L1CAM (L1 cell adhesion molecule)
Diseases named in the same sentence as L1CAM in open-access papers (continued):
Sharing a sentence is not in itself a finding about the gene and the disease.
ovarian carcinoma (continued). "In mouse models for ovarian cancer, pancreatic cancer and cholangiocarcinoma, L1CAM antibodies significantly prolonged survival, reduced ascites formation and reduced tumor burden." (PMID 29152102, 2017). "It has been shown in previous reports that L1CAM is expressed on every ovarian surface epithelium cell, whereas it appears only on a subset of ovarian cancer cells, mainly of advanced stages." (PMID 27832351, 2017). "In ovarian cancer L1CAM expression was previously studied by immunohistochemistry (IHC) on paraffin-embedded samples and by enzyme-linked-immunosorbant assay (ELISA) as well in lysates of serous ovarian cancers as in the corresponding ascitic fluid." (PMID 27174921, 2016). "We have included a summary of all relevant published studies on L1CAM expression and ovarian cancer with the main results." (PMID 27174921, 2016). "The L1CAM mRNA expression in ovarian cancer also differed according to platinum response during first line chemotherapy." (PMID 27174921, 2016). "In the present work we assessed L1CAM expression on the transcriptome level with the highly sensitive quantitative real-time PCR (qRT-PCR) to define its relevance in ovarian cancer biology." (PMID 27174921, 2016). "Another in vivo ovarian cancer study indicated possible therapeutic relevance for radioimmunotherapy combining anti-L1CAM antibodies (chCE7 and L1-11A) with 67Cu-radiotherapy." (PMID 27074785, 2016). "For example, L1-CAM has been shown in pancreatic and ovarian carcinoma cells to augment protection from apoptosis and to contribute to chemoresistance." (PMID 26761817, 2016). "L1CAM mRNA expression appears to play a substantial role in the pathophysiology of ovarian cancer that is translated into poor clinical outcome." (PMID 27174921, 2016). "In survival analysis median L1CAM mRNA expression obtained in the entire cohort of ovarian cancer samples was used as a cut-off to distinguish between high and low L1CAM mRNA expression." (PMID 27174921, 2016). "Especially with regard to the possible treatment option with humanized L1CAM antibodies, head to head comparisons are however needed to define the most reliable method to determine the L1CAM status in ovarian cancers." (PMID 27174921, 2016). "We found a significant correlation of the L1CAM mRNA expression in ovarian cancer with FIGO stage and tumor grading." (PMID 27174921, 2016). "Subgroup analysis demonstrated similar effect of L1CAM expression on cancer types for PFS/RFS in ovarian cancer, gastric cancer, and NSCLC." (PMID 27833079, 2016). "L1-CAM has been previously documented to be over-expressed in many solid tumors including ovarian cancer." (PMID 26761817, 2016). "This is the first study where the L1CAM expression was measured on a transcriptional level by real-time PCR in human ovarian cancer with the aim of a more precise and reproducible quantification of L1CAM activity." (PMID 27174921, 2016). "Its upregulation on ovarian cancer cells with high peritoneal seeding potential indicates a role for L1CAM in PM formation." (PMID 27074785, 2016). "A total number of 138 ovarian cancer samples and 32 healthy ovarian tissue samples were analyzed for L1CAM mRNA expression." (PMID 27174921, 2016). "Combination of anti-L1CAM 177Lu-RIT with PTX is a more effective therapy resulting in a prolonged overall survival of human ovarian carcinoma-bearing nude mice compared with either monotherapy." (PMID 26116117, 2014). "An antibody against the extracellular domain of the L1CAM was recently developed and was shown to inhibit the growth of L1CAM-expressing tumor cells including pancreatic and ovarian carcinoma and an intrahepatic cholangiocarcinoma in animal models." (PMID 25294816, 2014). "Conversely, the downregulation of L1CAM in IGROV1 ovarian cancer cells significantly inhibited cell proliferation." (PMID 24660028, 2014).
ovarian carcinoma (continued). "In this study, we asked for the first time if the efficacy of L1CAM-targeted ovarian cancer RIT can be further improved by the introduction of PTX into the therapy scheme." (PMID 26116117, 2014). "In line with our study, up-regulation of L1cam was also found in other tumors, such as ovarian cancer, colorectal cancer, anaplastic thyroid carcinoma and intrahepatic cholangiocarcinoma." (PMID 23806079, 2013). "Ectopic expression of L1cam in ovarian carcinoma cells activates Erk and FAK signal pathways to promote cellular migration, invasion and apoptosis resistance." (PMID 23806079, 2013). "Our present findings that the expression of L1CAM was increased during progression of human ovarian carcinomas are in line with this evidence." (PMID 21541352, 2011). "In melanoma and ovarian carcinoma the cleaved L1CAM ectodomain can play a role in tumor progression, conferring cellular properties that are important in advanced stages of cancer progression including enhanced motility and invasivenes." (PMID 21600041, 2011). "A further study suggested that L1CAM may contribute to cisplatin resistance in epithelial ovarian cancer (EOC)." (PMID 41301764, 2025). "Furthermore, its expression correlated with the mRNA levels of several stem-cell and EMT-related genes including LIN28, OCT4, VIM, and TGFB1 in the L1CAM+/CD133+ cell populations derived from ovarian cancer IGROV1 and SKOV3ip cells." (PMID 40429728, 2025). "To address whether L1CAM plays a similar role in ovarian cancer, we examined the expression levels of L1CAM in HGSC by analyzing L1CAM RNAseq expression from The Cancer Genome Atlas (TCGA) data set." (PMID 36509990, 2022). "To test whether ovarian cancer cells and L1CAM-expressing FTSECs can colonize the ovary, we developed an ovary-tumor co-culture system." (PMID 36509990, 2022). "Moreover, L1CAM in combination with CD133 characterizes a new specific ovarian cancer stem cell (CSC) population, displaying increased radioresistance, enhanced spherogenic and clonogenic property, self‐renewal capacity and superior tumour growth in nude mice." (PMID 35429348, 2022). "In light of the known correlation of L1CAM with ovarian cancer aggressiveness, these findings, once confirmed in patient-derived tissue, might implicate L1CAM/CD133-positive CSC in the malignant properties of this tumor type." (PMID 32429448, 2020). "Since L1CAM was also reported to induce IL1β in ovarian cancer, L1CAM-induced resistance in this cancer may be regulated through a similar mechanism." (PMID 31455004, 2019). "Nine studies on L1CAM-FL focused on interactions and downstream functions of the cytoplasmic domain of the full length protein (FL-CT), mostly focusing on colorectal cancer, ovarian carcinoma and pancreatic cancer." (PMID 31455004, 2019). "Furthermore, heterotypic interactions of L1CAM-ECD from ovarian cancers and α3 integrins of endothelial cells, promotes angiogenesis through the vascular endothelial growth factor receptor 2 (VEGFR-2)." (PMID 31455004, 2019). "Aberrant expression of L1CAM is found in many types of human cancers, including colorectal cancer, melanoma, breast cancer, ovarian carcinoma, kidney carcinoma, neuroblastoma, gastrointestinal stromal tumors (GISTs), pancreatic carcinoma, Schwannoma, and glioma." (PMID 30116755, 2018). "Of note, L1CAM also contributes to the transendothelial migration of ovarian cancer cells." (PMID 28134764, 2017). "As it was mentioned, in ovarian cancer, the L1CAM shedding is a function of its surface expression." (PMID 27832351, 2017). "Interestingly, the inhibitory effect of L1-11A on ovarian cancer cell growth synergized with radioimmunotherapy based on the 67Cu-labelled anti-L1CAM antibody chCE7, thus implying the feasibility of combinatorial L1CAM-targeted treatments." (PMID 28134764, 2017).
ovarian carcinoma (continued). "The aim of this study is to assess the concentration of soluble forms of L1CAM in sera of patients with endometrial and ovarian cancer and verify the feasibility of sL1CAM as a marker of the disease and its correlation with clinicopathological parameters of the disease." (PMID 27832351, 2017). "L1CAM concentration positively correlated with ovarian cancer stage (p = 0.0152, R = 0.5618)." (PMID 27832351, 2017). "Therefore this study for the first time intended to investigate the clinical relevance of L1CAM determined on the transcriptome level by an alternative method, namely the quantitative real-time polymerase chain reaction (RT-PCR) in ovarian cancer." (PMID 27174921, 2016). "Univariate survival analysis of all 138 ovarian cancer patients using the median L1CAM mRNA expression as cut-off revealed that high levels of L1CAM had an adverse prognostic impact as well for progression-free (PFS) (p=0.002) as for overall survival (OS) (p=0.009)." (PMID 27174921, 2016). "This may be particularly relevant to targeting L1-CAM in ovarian cancer, which, like most solid tumors, appears to exhibit heterogenous antigen expression both within and between patient tumors." (PMID 26761817, 2016). "In this study, we investigated whether the efficacy of previously developed anti-L1CAM 177Lu-RIT against ovarian carcinoma can be further increased by its combination with the radiosensitising taxane PTX." (PMID 26116117, 2014). "Recently, we could show that radioimmunotherapy (RIT) with 177Lu-labelled anti-L1 cell adhesion molecule (L1CAM) monoclonal antibody chCE7 is effective in ovarian cancer therapy." (PMID 26116117, 2014). "The L1 cell adhesion molecule (L1CAM) was originally described as a protein of the nervous system and is highly expressed on numerous tumours such as neuroblastoma, colon carcinoma, melanoma, pancreatic adenocarcinoma and ovarian carcinoma." (PMID 26116117, 2014). "In OVMz ovarian carcinoma cells the level of L1CAM was also clearly reduced upon treatment." (PMID 24497324, 2014). "To assess whether the metastasis-promoting effect of FL-L1CAM was cell line-specific, we specifically and stably overexpressed one of the two L1CAM isoforms in lacZ-tagged human SKOV3ip-lacZ ovarian carcinoma and L-CI.5s T-lymphoma cells." (PMID 21541352, 2011). "Likewise, Drapkin and the group have shown that L1CAM contributes to the ability of transformed FT secretory cells to detach from the tube and contribute to ovarian cancer pathogenesis by upregulating fibronectin and integrin in malignant cells, and activating AKT and ERK pathways." (PMID 37106610, 2023). "In addition, analysis of the Pan-Cancer cohort of the TCGA database confirmed a significant positive correlation of L1CAM expression with fibronectin and integrin-ɑ5 (17 of 33 and 19 of 33 cancer types, respectively) expression in the majority of cancer types, including ovarian cancer." (PMID 36509990, 2022). "In addition, L1CAM is present in the bulk population of ovarian cancer cells." (PMID 31952346, 2020). "Finally, exosomal L1CAM is produced by patient-derived primary GBM cells and can be recovered from blood and ascites from ovarian cancer patients and may promote as platform L1CAM cleavage or systemic delivery vehicle of membrane-bound L1CAM forms." (PMID 31455004, 2019). "As already mentioned, L1CAM expressed on the surface of cancer cells is released to the body fluids and may be found in serum or ascites fluid of endometrial or ovarian cancer patients, as well as in the culture medium of many human and mouse L1-positive carcinoma cell lines." (PMID 27832351, 2017). "However, in ovarian cancer available IHC data on L1CAM are very poor." (PMID 27174921, 2016).
ovarian carcinoma (continued). "The L1CAM was recently identified as a key mediator of tumor progression due to its upregulation in a variety of human tumors, including melanomas, renal cancer, lung cancer, mesotheliomas oral cancer, ovarian carcinoma, and hepatocellular carcinoma with high correlations with cancer progression." (PMID 25294816, 2014). "L1CAM promoted FTSEC sphere formation and survival of ovarian cancer cells and immortalized FT cells." (PMID 36509990, 2022). "Here, we use CAR T cells targeting the glycosylated CE7 epitope of the L1 cell adhesion molecule, L1CAM (formerly CD171), which is specifically expressed on tumor cells and a promising target for neuroblastoma and ovarian cancer." (PMID 33801448, 2021). "L1 cell adhesion molecule (L1CAM) confers metastasis-initiating abilities and chemoresistance in CRC and radioresistance in ovarian cancer." (PMID 34202399, 2021). "Some study suggested that Twist promotes platinum resistance in ovarian cancer via activation of collagen type XI alpha 1 (COL11A1), GAS6, L1CAM, and Akt signaling." (PMID 33076245, 2020). "Some of them, such as MUC4, CD44, L1CAM, ALCAM and P-cadherin, promote the malignant tendency of ovarian carcinoma cells." (PMID 30274262, 2018). "In a study using ELISA to detect the serum L1CAM level in a few patients with endometrial and ovarian cancer compared to non-cancerous patients, the serum L1CAM level was found to be lower in cancer-bearing patients than in healthy women." (PMID 40870967, 2025). "Additionally, L1CAM expression, together with CD133 expression, defines the cancer stem cell population in glioma and ovarian cancer." (PMID 37566075, 2023). "L1 cell adhesion molecule (L1CAM), an important molecule and marker found in ovarian cancer for poor prognosis, has been found to be related to adhesion and invasion, and an antibody against L1CAM could significantly suppress this progression." (PMID 36614904, 2022). "The important role of L1CAM in the development and propagation of HGSC suggests that L1CAM may have potential as a target to prevent ovarian cancer dissemination." (PMID 36509990, 2022). "Interestingly, indirect evidence suggested a cooperation between L1CAM and the FGFR signaling machinery also in ovarian cancer cell proliferation." (PMID 34645505, 2021). "We deployed monospecific murine instead of polyclonal human T cells for CAR T cell generation to evaluate second generation L1CAM- and HER2-specific CARs with different spacer length and either the CD28 or 4-1BB co-stimulatory domain in mouse models of neuroblastoma and ovarian carcinoma." (PMID 33801448, 2021). "Given that ovarian cancer stem cells (OCSC) are viewed as main players in these events, we asked whether L1CAM plays a role in OC stemness and in OCSC-driven tumor progression." (PMID 34645505, 2021). "L1CAM was the most up-regulated single gene, known to be a negative prognostic factor in ovarian cancer, therefore fitting to the worse outcome of patients with high Nectin 4 expressing tumors in our study." (PMID 31137558, 2019). "Surprisingly however, L1CAM-FL, but not L1CAM-SV, confers metastasis in ovarian cancer, CRC, fibrosarcoma, and T-cell lymphoma." (PMID 31455004, 2019). "What is important, the poor clinical outcome for patients with L1CAM-positive ovarian cancers is similar irrespective of the tumor histological type." (PMID 27832351, 2017). "Again, like in the previous group, we have not analyzed the cell membrane expression of L1CAM in ovarian cancer patients and we cannot express the percentage of L1CAM-positive cancers among our patients." (PMID 27832351, 2017). "We and others have shown that the L1-cell adhesion molecule (L1-CAM) is highly over-expressed in ovarian cancer, while absent in normal ovaries, and that its expression on tumors is associated with poor clinical outcome." (PMID 26761817, 2016).
ovarian carcinoma (continued). "While it is known that L1CAM is expressed in HGSC16,17, it is not known at what stage of ovarian cancer development L1CAM is expressed and whether or not it has a functional role in transformation or dissemination." (PMID 36509990, 2022). "In vitro encounter with HER2+ SKOV3 ovarian carcinoma cells induced Ifng and Il2 release from all four HER2-specific CAR T cell designs regardless of co-stimulatory moiety, but designs using 4-1BB co-stimulation also induced lower cytokine levels as in CAR T cells targeting L1CAM." (PMID 33801448, 2021). "Additionally, L1CAM has been found to be a potential biomarker in several types of human cancers 21,23, including esophageal squamous cell cancer (ESCC) 22, gastrointestinal stromal tumors (GIST) 24, uterine and ovarian cancers 25 and other less common types of cancer." (PMID 32742486, 2020).